XCR1 (X-C motif chemokine receptor 1)
Diseases named in the same sentence as XCR1 in open-access papers (continued):
Sharing a sentence is not in itself a finding about the gene and the disease.
tumor (continued). "Here, we engineered an anti-XCR1 antibody (Ab) and IFN mutein (IFNmut) fusion protein (XCR1Ab-IFNmut) to determine whether systemic delivery could drive selective and sustained type I IFN signaling in cDC1s leading to anti-tumor activity and, in parallel, reduced systemic toxicity." (PMID 37942313, 2023). "Indeed, fully differentiated cDC1 recruited from blood or surrounding tissue might be the predominant origin of intratumoral cDC1s that accumulate in response to XCL1 and CCL5 produced by tumor NK cells because cDC1 precursors express only low levels of transcripts for CCR5 and XCR1." (PMID 30352680, 2018). "Unexpected, we did not observe significant XCR1 RO, or a gain in IFN activity in cDC1-targeted cells in the spleen or tumor, following 3 injections with the XCR1Ab-IFNL53A fusion." (PMID 37942313, 2023). "Tumor-infiltrating B cells represented between 0.05% and 0.6% of CD45+MHCII+ and did not stain positive for CD11c, XCR1 and IRF8." (PMID 32461349, 2020). "In contrast to CCL5, which acts on the chemokine receptor CCR5 and can promote migration of tumor-promoting immune cells such as macrophages and Treg cells 32, 33, XCL1 acts as a ligand for XCR1 and acts on XCR1+ cDC1s but not on other cells." (PMID 30352680, 2018). "Consistent with murine data, expression of HLA-DR, CD86, CD40 and PDL1 was significantly increased in CD141+ cDC1 DCs (equivalent to mouse XCR1+) and CD1c+ cDC2 DCs (equivalent to mouse CD11b+), but not in pDCs, both pre- and post-Flt3L, upon co-culture with NDV-preinfected tumor cells." (PMID 36418317, 2022).
cancer (39 papers, 2016 to 2025). A tumor composed of atypical neoplastic, often pleomorphic cells that invade other tissues. "(i) Tal-PDT-induced ferroptosis of cancer cells was associated with the induction of proliferative CD8+ Tpex cells possibly through the XCR-1+ DC maturation in the proximal dLN." (PMID 39842944, 2025). "As a result, the constitutive expression of XCR1 in tumor tissues can be used as a clinical diagnostic and prognostic indicator of pan-cancer." (PMID 37895310, 2023). "And in patients with advanced cancer, the reduction in or loss of XCR1 was always accompanied by lymph node metastasis and the distal metastasis of tumor cells." (PMID 37895310, 2023). "In addition, we also found that the gene set “cell adhesion molecules” was also enriched in LIHC, which also confirms previous reports that the expression of XCR1 is associated with tumor cell metastasis and spread in the later stages of cancers." (PMID 37895310, 2023). "Overall, our pan-cancer analyses of XCR1 have elaborated the landscape of XCR1 expression with the clinical prognosis and immune cell infiltration, which provide a predictive biomarker in pan-cancer, especially in LIHC, KIRC, LUAD, HNSC, and COAD." (PMID 37895310, 2023). "To discriminate the cell types that express XCR1, we analyzed the distribution of XCR1 in different types of cancer." (PMID 37895310, 2023). "The differential expression of XCR1 in different tumor stages suggests that XCR1 can be used as a clinical staging marker to assist in cancer diagnosis and treatment." (PMID 37895310, 2023). "We found that in most common cancer types, XCR1 expression levels were significantly lower in almost all stages, including in COAD, LIHC, LUAD, LUSC, and THCA." (PMID 37895310, 2023). "It was concluded that in pan-cancer, XCR1 expression can promote the infiltration of DCs and CD8+ T cells, which indicates a better survival expectation and potential sensitivity to immunotherapy." (PMID 37895310, 2023). "In order to further elucidate the mutational characteristics and biological functions of XCR1 in tumor occurrence and progression, we investigated the genetic alteration status of XCR1 in pan-cancer based on the cBioPortal database." (PMID 37895310, 2023). "In this work, we screened all chemokine receptors in pan-cancer and discovered X-C Motif Chemokine Receptor 1 (XCR1) as a reliable immunological and prognostic biomarker in pan-cancer using bioinformation." (PMID 37895310, 2023). "We further analyzed the characteristics of XCR1 in pan-cancer, including expression difference, correlation between expression levels and survival, genetic alterations, immune cell infiltration, and related signal pathways." (PMID 37895310, 2023). "This suggests that the low expression of XCR1 is closely related to the occurrence, poor development, and spread of cancer cells." (PMID 37895310, 2023). "In the clinical stage analysis of pan-cancer, it was found that the low expression of XCR1 means the progression of the tumor." (PMID 37895310, 2023). "The expression of XCR1 was positively correlated with CD8+ T cells in most cancers, such as PAAD (Rho = 0.620), STAD (Rho = 0.556), KIRP (Rho = 0.411), TGCT (Rho = 0.406), etc.." (PMID 37895310, 2023). "The results showed that the deletion of the XCR1 genes hindered the migration ability of cancer cells, as the number of migrating cells was reduced in the transfected group." (PMID 37816979, 2023). "Among all the chemokine receptors, only XCR1 was closely related with the hazard ratio in most types of cancers." (PMID 37895310, 2023). "We then investigated the relationship between XCR1 expression and immune cell infiltration levels in diverse cancer types." (PMID 37895310, 2023). "We found that XCR1 was related to a good prognosis in pan-carcinoma and showed a positive correlation between XCR1 expression and immune cell invasion after further data mining." (PMID 37895310, 2023).
cancer (continued). "NK cells that recruit cDC1 cells via the chemokine receptor X-C motif chemokine receptor 1 (XCR1) were identified and found to promote cancer immune control." (PMID 36154923, 2022). "DC-targeting as a route to enhance the potency of cancer vaccines has been explored previously, with targeting of antigen to DC-specific markers such as XCR1, Clec9A and DEC205." (PMID 34944809, 2021). "We therefore determined that adding cancer cells two days following GM-CSF allowed for maximal differentiation of CD103+XCR1+ DC1s in the presence of cancer cells." (PMID 34847189, 2021). "On the other hand, we considered using XCL1 itself as an adjuvant to attract XCR1-expressing cDC1s into the injection site of cancer vaccines for efficient antigen delivery to cDC1s." (PMID 34885241, 2021). "Recent studies have also demonstrated the importance of XCL1/XCR1 in cancer cell proliferation, migration, and invasion." (PMID 33377624, 2021). "In the Cancer Genome Atlas (TCGA) test dataset, eight genes were detected, and six of them were survival associated (DPP4, FFAR4, RASA3, RASGRF1, XCR1, and STX11)." (PMID 34760708, 2021). "In this study, we aim to improve cancer peptide vaccination by targeting Ag peptides selectively to a dendritic cell (DC) subset, XCR1-expressing DCs (XCR1+ DCs), with high ability to support CD8+ T-cell responses." (PMID 32066911, 2020). "We aimed to deliver a cancer Ag peptide to XCR1+ DCs with high cross-presenting activity, by using a fusion protein, XCL1-OT-I, to carry the OT-I peptide and a chemokine, XCL1." (PMID 32066911, 2020). "XCR1+ DCs can also facilitate anti-cancer immune activity in response to cancer treatments such as radiotherapy, chemotherapy and photodynamic therapy, which are all known to induce immunogenic cell death (ICD)." (PMID 32121071, 2020). "Cancer Ag targeting to XCR1+ DCs should be a promising procedure as a combination anticancer therapy with immune checkpoint blockade." (PMID 32066911, 2020). "Given the conserved expression pattern of XCR1, peptide delivery targeted to cDC1s or XCR1+ DCs should be applicable as a cancer immunotherapy by overcoming the limited effects of ICIs." (PMID 32066911, 2020). "Similar results showing XCR1-mediated cell migration were reported in other cancer cells including EOC, NSCLC, and OSCC." (PMID 33374849, 2020). "Careful consideration on the most effective interventions to enhance migration, activation, maturation and function of XCR1+ DCs is likely to be vital to unleash their full anti-cancer potential." (PMID 32121071, 2020). "Previous studies have exploited Xcr1-antigen targeting either in the context of Flu or cancer vaccines." (PMID 30863405, 2019). "Specifically, Tal-PDT-derived ferroptosis of cancer cells induced XCR-1+ cDC1s and Tpex cells, which may give rise to the effector T cells in vivo." (PMID 39842944, 2025). "In summary, our data revealed the important role of XCR1 in the prognosis of cancers, which could also be used as a sensitive biomarker for tumor immunotherapy." (PMID 37895310, 2023). "In addition, the results of the cell migration assay by Transwell showed that the deletion of the XCR1 genes hindered the migration ability of cancer cells, as the number of migrating cells was reduced in the transfected group." (PMID 37816979, 2023). "However, the role and mechanism of XCR1 in tumor progression and the immune–cancer interaction are still unclear." (PMID 37895310, 2023). "Here, we conducted a pan-cancer analysis of all chemokine receptors and found that only XCR1 could serve as a prognostic marker in most cancers." (PMID 37895310, 2023). "Among above cancers, we further explored the multifactorial Cox regression analysis of XCR1." (PMID 37895310, 2023).
cancer (continued). "Here we have reported a novel strategy to increase the efficiency of peptide-based cancer vaccines, using a dual approach of targeting the vaccine construct to XCR1+ cDC1 and enhancing antigen entry into the cross-presentation pathway through the use of an endosomal escape CPP." (PMID 34944809, 2021). "In other tissues, XCR1+ DCs cross-present antigen and contribute to immunity against viruses and cancer, however the roles of XCR1+ DCs and XCR1 in the intestine are unknown." (PMID 27005831, 2016). "Furthermore, XCR1 was not a significant high-risk gene in any type of cancer, suggesting the universal protective role of XCR1 in human cancer." (PMID 37895310, 2023). "Simultaneously, we found that the expression of FASN was correlated with various chemokines (e.g., XCL2 and CCL14) and chemokine receptors (e.g., XCR1 and CCR8) in different cancers." (PMID 36555243, 2022). "Here we focus on the recent progress in DC-based cancer vaccines and especially the use of the XCR1 and its ligand XCL1 axis for the targeted delivery of cancer vaccines to cross-presenting dendritic cells." (PMID 34065346, 2021). "Other genes overexpressed in Cluster 1 were chemokine and cytokine related genes (CCL15, CCL18, TNF, IL11RA, XCR1), the immune checkpoint protein PD-1 (PDCD1), and cancer-related genes (SSX1 and MAGEA4)." (PMID 33298930, 2020). "Potent antitumour activity of XCL1-OT-I should come from its ability to target Ag to XCR1+ DCs, which are crucial Ag-presenting cells for generation of CD8+ T-cell responses against cancers." (PMID 32066911, 2020). "CD6, CCL19, CD40LG, XCR1, MAGEA1, ATM and CCL19 genes were significantly differentially expressed in MET-altered cancers." (PMID 33437521, 2020). "It would also be helpful to judge and rule out special cases in diagnosis and treatment if XCR1 was used as a biomarker for cancer detection." (PMID 37895310, 2023). "The results of the present study demonstrated that ESTIMATE algorithm-based stromal and immune scores may be a credible indicator of cancer prognosis and IL10 along with XCR1 may be a potential key regulator for the TME of ccRCC." (PMID 31781309, 2019). "As CD103 is normally used to identify DC1s, the difference of function between CD103+XCR1+ DCs and CD103-XCR1+ DCs in cancer is not well-established." (PMID 34847189, 2021). "Compared with normal tissues, the expression of XCR1 in pan-carcinoma is generally lower, except in KIRC, although it is not clear whether the XCR1 decline is due to a decrease in XCR1 expression by tumor cells or a decrease in cDC1 invasion." (PMID 37895310, 2023). "Similarly, the XCR1-DTR model allows exclusive depletion of developmentally normal XCR1+ DCs following diphtheria toxin injection, although has not yet to our knowledge been used in cancer models." (PMID 32121071, 2020).
infection (30 papers, 2013 to 2024). The state of being infected such as from the introduction of a foreign agent such as serum, vaccine, antigenic substance or organism. "Consistent with this, compared to wildtype controls, splenic Xcr1+ Bcl3-deficient cDC1 cells were defective in presenting Ova antigen to OT-I cells both for Ova257-264 peptide and after infection with Ovalbumin-expressing T. gondii." (PMID 36318581, 2022). "The elite controllers expressed unique transcripts early in infection that were closely associated with specialized cross-presentation between XCR1+ DCs and antigen-specific CD8+ T cells (XCL1)." (PMID 28350860, 2017). "Taken together, these data suggest that immature chicken XCR1+ cDCs may limit infection by viruses by expressing genes encoding antiviral molecules; however, optimal antigen presentation is co-incident with the down regulation in expression of these genes." (PMID 37954617, 2023). "By contrast, the pool of genes induced during ΔF2 Nig06 infection is mainly involved in the mounting of an immune response: Trem1, Kng1, Nfatc2ip and Xcr1 are particularly implicated in mediation of inflammation, cytokine induction and leukocyte chemoattraction." (PMID 23469251, 2013). "To test this idea, we inoculated Xcr1-Cre+Ifnar1fl/fl mice with RRV-gp33; DC1s from these mice specifically lacked IFNAR1 expression and were more susceptible to RRV infection than Cre– littermate controls." (PMID 39535221, 2024). "Using this methodology were were able to sufficiently deplete the XCR1 + cDC1s from the lymph node draining the immunization and infection." (PMID 38514656, 2024). "CD8+ T cells remained naïve in the early infection stage until lymph node-resident XCR1+ DCs received licensing signals from activated CD4+ T cells." (PMID 36936763, 2023). "Seven days after oral infection with RV, XCR1.IFNAR1KO mice showed comparable increases of total CD45+ and CD8 T cell numbers to cre negative littermate controls." (PMID 35464475, 2022). "At this time point, XCR1 expression was less pronounced after infection with wild-type RCMV which might indicate that Δvxcl1 RCMV could be less successful in attracting and subsequently infecting DC." (PMID 38077365, 2023). "Also, RCMV infection led to a rapid reduction of Xcr1 transcription which is likely not only due to the infection process but also to XCR1 recycling." (PMID 38077365, 2023). "Here, we investigated whether rat CMV can infect XCR1+ DC and if infection of DC alters expression of cell surface markers and migration behavior." (PMID 38077365, 2023). "We observed no impairment of memory T‐cell formation after subcutaneous MCMV infection after depletion of pDCs, Langerhans cells or, in contrast to data derived from mice with genetic defects in cross‐presenting DCs (and thus throughout the time course of infection), XCR1+ DCs." (PMID 34003499, 2021). "In this regard, we suggest that our observation of upregulated XCL1 only in elite controllers during early infection might indicate communication between cross-presenting XCR1+DCs and antigen-specific CD8+ T cells that should be investigated in future studies." (PMID 28350860, 2017). "To determine if we could experimentally overcome this deficient RRV-specific CD8+ T-cell response, we treated animals in the foot with an anti-IFNAR1 monoclonal antibody (mAb) or used Xcr1-Cre Ifnar1fl/fl mice to modulate the infection of antigen-presenting cells in the DLN." (PMID 39535221, 2024). "Furthermore, these cells did not accumulate with disease progression as observed with other mononuclear cell populations (RPM, CD11b+ DC, CD103+/XCR1+ DC), displayed similar kinetics of EdU incorporation and decay between infection phases, and were undetectable in the lungs of uninfected mice." (PMID 30365557, 2018).
infection (continued). "In our screen, all chemokine receptors showing increased PD-1 expression on day 4 post infection either match chemokines secreted by dendritic cells (CCR5, CXCR3) or respond to chemokines that also attract dendritic cells (XCR1)." (PMID 37301772, 2023). "In contrast to mock infection, RCMV wild-type and Δvxcl1 mutant virus-infected DC showed significantly decreased XCR1 expression at 8 and 24 hpi." (PMID 38077365, 2023). "Conventional DC1 cells (XCR1, BATF3 -expressing PBMC myeloid population 6) were less abundant than cDC2s and changed relatively little in abundance during infection." (PMID 35271298, 2022). "Infection with GFP-expressing C. rodentium indicated uptake of fluorescent signal also in dendritic cells of both migratory (CD103+) and cross-presenting (XCR1+) phenotypes." (PMID 35140345, 2022). "Upon challenge infection, we noted that CCR5 and XCR1 expression on CCR2+Ly6C+ monocytes was significantly increased." (PMID 34516896, 2021). "For example, upon secondary infection with Listeria, NK cells were rapidly activated, serving as an important early source of IFN-γ to induce XCR1+DCs-mediated reactivation of memory CTLs." (PMID 32626664, 2020). "In later infection stages, both T cell types translocate to the LN paracortex where they both interact with a distinct non-infected XCR1+ DC population." (PMID 38932162, 2024). "After anti-IFNAR1 treatment, the Venus protein signal increased in several myeloid cells in the DLN, including both DC1s (CD11c+ MHC-II+ Xcr1+) and DC2s (CD11c+ MHC-II+ Sirpα+), although we cannot definitively distinguish direct infection from phagocytosis of infected cells using this assay." (PMID 39535221, 2024). "ILC1s produce optimal IFN-γ in a signal transducer and activator of transcription 4 (STAT4)-dependent manner via tissue-resident X-C motif chemokine receptor 1-positive conventional dendritic cells (XCR1+ cDC1), thereby limiting viral replication at the initial site of infection." (PMID 37908364, 2023). "Later during infection, non-infected CD8α+ XCR1+ cDCs loaded viral antigens through cross-presentation and presented antigens to both T cell subsets through MHC-1 and MHC-II." (PMID 36936763, 2023). "Despite the impact of MCMV replication on DC accumulation in lymph nodes, systematic depletion of different DC subsets during the first few days of infection revealed no obvious role for pDC, Langerhans cells or XCR1+ DCs in facilitating inflationary memory T‐cell formation." (PMID 34003499, 2021). "Furthermore, many chemokine receptors like CCR4, CCL14, XCR1 along with the adaptor molecules CRKII and ELMO1 were downregulated during initial and mid stages of infection, and in contrast, some G protein signaling molecules such as GNAI, GNB1, FAK and FAK2 were upregulated in infected fish." (PMID 33177569, 2020). "Imaging of T cells and cDC1s during vaccinia virus infection showed a similar phenomenon and it was observed that multiple DC subsets could prime CD8 T cell responses early during infection; however, later in infection CD8 T cells interacted with only XCR1-expressing cDC1s73." (PMID 28184299, 2017). "In turn, these XCR1+ DCs are potent in the cross-presentation of viral antigens to CD8+ T cells, and are crucial in driving non-replicative MVA infection." (PMID 38932162, 2024). "In this context, non-infected XCR1+ (CD8α+) DCs were critical and responsible for the initial activation of naive CD8+ T cells by cross-priming at later time points of infection and were supported by previously primed CD4+ T cells." (PMID 32765505, 2020). "Human XCR1+ DCs uniquely respond to stimulation with HCV by producing large amounts of IFN-III in a TLR3-dependent manner, irrespective of their own infection." (PMID 25400632, 2014).